MEG3 (maternally expressed 3)
Diseases named in the same sentence as MEG3 in open-access papers (continued):
Sharing a sentence is not in itself a finding about the gene and the disease.
tumor (continued). "We found that Meg3 levels were decreased in tumor tissues from CRC patients, as well as in AOM/DSS-induced CRC mice, compared to the corresponding control tissues." (PMID 34934045, 2021). "Our previous study have focused on the relationship between MEG3 and tumor cells function and its molecular mechanism." (PMID 34238211, 2021). "LncRNA maternally expressed 3 (MEG3) effectively repressed the tumor formation ability of CC cells in vivo and hampered proliferation, whereas it elevated apoptosis of CC cells in vitro." (PMID 33817293, 2021). "Given that Meg3 functions as a critical tumor suppressor in cancer, the GEO datasets were analyzed to assess Meg3 expression in CRC." (PMID 34934045, 2021). "LncRNA MEG3 (MEG3) has been characterized as a tumor suppressive lncRNA in different types of cancers, and MEG3 upregulation inhibits cancer development." (PMID 35201451, 2021). "For example, the lncRNA MEG3 exerts its tumor suppressor function through motifs within its secondary structure rather than its primary sequence." (PMID 33435206, 2021). "MEG3 was originally considered a tumor suppressor that plays an important antiproliferative role in cancer cells." (PMID 34222244, 2021). "lncRNA maternally expressed gene 3 (MEG3) is localized on human chromosome 1432.3 and can be widely expressed in normal human tissues, with decreased expression in some tumor cells, and MEG3 overexpression can inhibit tumor cell proliferation and migration." (PMID 34222244, 2021). "As a tumor suppressor gene, MEG3 inhibits the occurrence and development of tumors by inhibiting the proliferation, migration, and apoptosis of cancer cells." (PMID 34978518, 2021). "Compared to normal tissues, MEG3 expression level was significantly lower in tumor tissues (p < 0.05)." (PMID 35201451, 2021). "Our study determines the heterogeneity of the primary and PDAC tumor cells and reveals that MEG3 positive tumor cells are leading the metastasis of PDAC." (PMID 34055623, 2021). "Deletion of MEG3 increased tumor cell growth and enhanced cell proliferation in normal human astrocytes." (PMID 34322395, 2021). "Maternally expressed gene 3 (MEG3) is located on human chromosome 14q32.3, and defined as a tumor suppressor in several human cancers, such as nasopharyngeal carcinoma, breast cancer and ovarian cancer." (PMID 34130697, 2021). "We screened microarrays that characterized the gene expression profiles between PDAC and normal pancreatic tissues from the GEO database and found a downregulated lncRNA, MEG3, to be a tumor suppressor." (PMID 33299646, 2020). "Meg3 is the first lncRNA that was identified as having tumour suppressive function by inhibiting the proliferation of cancer cells and modulating the Rb pathway." (PMID 32052546, 2020). "DLK1/MEG3 locus promoted somatotroph differentiation and inhibited tumor proliferation in PIT1(+) patients, furthermore, the level of DLK1 played a critical role in the trend of somatotroph or lactotroph differentiation." (PMID 33472171, 2020). "In order to further investigate the biological functions of lncRNA MEG3, cell migration assay and tumor xenografts in nude mice were conducted." (PMID 31938020, 2020). "Our study demonstrated the important roles of the protective metabolism changes and their relationship with the tumour suppressor lncRNA MEG3 during the OLP malignant transformation process." (PMID 31793175, 2020). "In PNETs, tumor hypermethylation and silencing of long noncoding MEG3, determined activation of miR183/BRI3 axis, and cell proliferation due to c-MET oncogene activation." (PMID 33384663, 2020). "A decrease in MEG3 expression has been found in many human tumors, including in the stomach, tongue, prostate, lung, and bladder, and it exerts its function in tumor cell proliferation, migration, and invasion." (PMID 32596158, 2020).
tumor (continued). "Three CpG probes located in the MEG3-DMR showed significantly lower methylation levels in metastatic tumor tissues compared to normal liver tissues using Mann-Whitney U analysis." (PMID 33282720, 2020). "In the present study, we also found that MEG3 expression was lower in tumor tissue than adjacent normal tissues from patients with CRC." (PMID 32219064, 2020). "In PDAC, it is possible that ectopic expression of MEG3 inhibits tumor invasion and metastasis by regulating miRNA expression." (PMID 33299646, 2020). "In PC, MEG3 is characterized by a downregulated expression, and increased expression has an inhibitory effect on tumor growth." (PMID 33552133, 2020). "Previous studies have reported that MEG3 was associated with EZH2, and that EZH2 was a tumor target, which acted as an oncogene in NB." (PMID 33061817, 2020). "MEG3 has a lower expression in OS tissues compared with adjacent non‐tumor ones which is also found expressed at low levels in OS cell lines." (PMID 32249459, 2020). "Many studies suggest MEG3 as a tumor suppressor, largely due to the observation that MEG3 expression is lower in tumor tissue compared to normal tissue." (PMID 32612992, 2020). "MEG3 (Maternally expressed 3) lncRNA has been reported to act as a molecular decoy for tumor-related microRNAs such as miR-421." (PMID 32575858, 2020). "Methylated MEG3, lowly expressed MEG3, large tumor size (≥2 cm), advanced TNM grade and lymphatic metastasis were potentially symbolic of poor prognosis among BC patients (P < .05)." (PMID 32618397, 2020). "According to research reports, excessive MEG3 can inhibit tumor growth through a variety of mechanisms." (PMID 33256840, 2020). "One of the functions of MEG3 is regulation of the blood–tumor barrier permeability through the MEG3/miR-3305 ̈Cp/RUNX3 axis." (PMID 32650527, 2020). "Currently, the supplement of MEG3 acted as a tumor suppressor, showing as the blockage of cell-cycle, migration, invasion, and proliferation in MEN cells." (PMID 33251130, 2020). "Consistently, the methylation rate of MEG3 in BC tissues was also obviously higher than that in adjacent non‐tumor tissues." (PMID 32618397, 2020). "Ki-67 expression was indeed significantly decreased in the MEG3 groups, indicating that the tumor suppression by MEG3 was at least partially mediated through proliferation inhibition." (PMID 33299646, 2020). "MEG3 levels were downregulated in EC tissues compared with that in adjacent non-tumor tissues, and EC patients with low MEG3 expression exhibited shorter overall survival compared with patients with high expression levels." (PMID 33363153, 2020). "Conversely, MEG3 was significantly less methylated in the tumor of smoker patients with clinical early-stage NSCLC, as compared to non-cancerous tissue." (PMID 32438606, 2020). "Recent studies have shown that expression of MEG3 is lost in multiple types of tumors, with lines of evidence strongly suggesting that MEG3 functions as a novel lncRNA tumor suppressor." (PMID 32295169, 2020). "C8orf58 is downregulated in HCC and coexpressed with MEG3 protein, which acts as a suppressor in tumor cells." (PMID 32316112, 2020). "Firstly, MEG3 can inhibit the proliferation of tumor cells and consequently induce apoptosis, which has been confirmed by in vitro experiments and animal models." (PMID 32669097, 2020). "Low MEG3 expression was significantly associated with advanced WHO grade, low Karnofsky performance score, isocitrate dehydrogenase (IDH) wild-type, and tumor recurrence, which led to poor overall survival." (PMID 32650527, 2020).
tumor (continued). "Prior studies demonstrated that MEG3 is located at human chromosome 14q32.3 and is a novel tumor-suppressor lncRNA in many tumors, including EC." (PMID 33363153, 2020). "For example, MEG3 impeded tumor growth of cervical carcinoma cells via promoting cell-cycle arrest and apoptosis." (PMID 33251130, 2020). "MEG3 functions as a tumor suppressor gene, and its re-expression inhibits cell proliferation and promotes apoptosis in human glioma and NSCLC cell lines." (PMID 32194993, 2020). "Results obtained showed a significant reduction of migration ability in MEG3-overexpressing tumor cells compared to the control (p < 0.001 and p = 0.004 for HEY and PEO1, respectively)." (PMID 32295169, 2020). "In vitro and in vivo preclinical studies supported a role for MEG3 as a tumor suppressor in HGSOC, possibly through modulation of the phosphatase and tensin homologue (PTEN) network." (PMID 32295169, 2020). "Maternally expressed gene 3 (MEG3) is a well-known lncRNA, and it is commonly considered to be a tumor suppressor." (PMID 33251130, 2020). "MEG3 is sometimes referred to as tumor suppressor because its overexpression promotes apoptosis and inhibits the proliferation of tumor cells." (PMID 32545342, 2020). "Differently, maternally expressed gene 3 (MEG3) was shown to function as a tumor suppressor in CSCC; in fact, MEG3 expression inhibited cell proliferation and promoted apoptosis in CSCC cells through modulating the level of miR-21-5p." (PMID 32429207, 2020). "For instance, MEG3 emerged as a powerful tool for prediction of tumor size and lymph node metastasis in patients with CSCC." (PMID 32429207, 2020). "Independent studies assessed MEG3 ability to inhibit tumor cell proliferation and induce cell apoptosis in different cell lines." (PMID 33142861, 2020). "The maternally expressed gene 3 (MEG3) is located in the human 14q32 chromosome, named as gene trap locus 2 in mouse, and widely investigated in tumour cases." (PMID 32436312, 2020). "LncRNA maternally expressed gene 3 (MEG3), located on human chromosome 14q32.3, is a tumor suppressor gene." (PMID 32420340, 2020). "Using qRT-PCR analysis, we discovered that the levels of MEG3 were significantly downregulated in HEC-50 and SPAC-1-L cells compared with EM cells, suggesting a potential tumor-suppressor role for MEG3 in aggressive EC cells." (PMID 33363153, 2020). "Accumulating evidence suggests that MEG3 is a tumour‐suppressing lncRNA and down‐regulated in multiple malignancies." (PMID 32436312, 2020). "Long noncoding RNAs, such as the tumor-suppressing MEG3, have been identified as regulators of various types of human tumors." (PMID 31212896, 2019). "Once the expression of MEG3 is restored or methylation is inhibited, tumor growth can be inhibited both in vivo and in vitro." (PMID 31584879, 2019). "Maternally expressed gene 3 (MEG3), a typical lncRNA located in the imprinted DLK1-MEG3 locus on human chromosome 14q32.3 region, often serves as a tumor suppressor in many cancers." (PMID 31085717, 2019). "MEG3 shRNA group had larger subcutaneous tumors and faster rate of tumor formation than NC shRNA group." (PMID 31320837, 2019). "In contrast to oncogenic lncRNAs, MEG3 was reported to be a tumor suppressor in UCC of the bladder and downregulation of MEG3 expression was associated with lower recurrence-free survival." (PMID 30813594, 2019). "We have additionally highlighted significantly changing lincRNAs that are common to both, namely the tumour suppressor MEG3, which is downregulated." (PMID 30611906, 2019). "In the present study, we selected tumor suppressor lncRNA MEG3 and its related molecules (miR-9-5p and SOX11) to explore the effects of those interactions on HCC." (PMID 31531526, 2019). "As a final example, lncRNA maternally expressed 3 (MEG3), which is located on human chromosome 14q32, has previously been reported as a tumor suppressor." (PMID 31516584, 2019).
tumor (continued). "Maternally expressed gene 3 (MEG3) belongs to DLK1-MEG3 imprinted locus on chromosome 14q32.3, acts as a tumor suppressor and found to be downregulated in various types of tumors and tumor cell lines." (PMID 31141943, 2019). "Meg3 has been shown to play an important role in the regulation of cellular proliferation and functions as a tumor suppressor in numerous tissues." (PMID 30765776, 2019). "The maternally expressed gene 3 (MEG3) represents the first recognized lncRNA tumor suppressor in pituitary adenomas." (PMID 31487906, 2019). "The results showed that the tumor size was smaller and the tumor formation rate was slower in MEG3 group than in vector group." (PMID 31320837, 2019). "Wound healing, transwell, colony formation and flow cytometry assays were used to analyze the effects of lncRNA MEG3 and methylation on tumor cell migration, invasion, proliferation and apoptosis." (PMID 31584879, 2019). "The results showed that tumor weight and volume in the MEG3 group were lower than those in the Con group (P<0.01)." (PMID 31584879, 2019). "When we combined all the data, we concluded that MEG3 served as a tumor inhibitor gene suppressing the migration, invasion, and proliferation of GC cells while promoting apoptosis." (PMID 31584879, 2019). "Re-expression of MEG3 inhibits tumor cell proliferation in culture and colony formation in soft agar." (PMID 31143763, 2019). "Various studies have reported the tumor-suppressor function of MEG3 and its deregulated expression in cancer cells." (PMID 31320614, 2019). "On the other hand, we observed a trend for shorter OS in patients with increased expression of the tumor suppressor MEG3." (PMID 30876483, 2019). "MEG3, the first to be found to have tumor suppressive effects, was a maternally imprinted gene located on chromosome 14q32.3 within DLK1–MEG3 locus." (PMID 31133028, 2019). "MiR-181a contends with MEG3, which acts as endogenous competitive RNA, to inhibit tumor progression." (PMID 30682861, 2019). "The MSP results showed that lncRNA MEG3 was hypermethylated in tumor tissues compared with normal tissues (P<0.01)." (PMID 31584879, 2019). "The lncRNA maternal expression gene 3 (MEG3), a maternally imprinted gene in the Dlk1-Gtl2 locus on chromosome 14q32.3 in human, is a tumor suppressor." (PMID 31717266, 2019). "As a maternally expressed imprinted gene, MEG3 has been found in various normal tissues (except for tumor cells)." (PMID 31888661, 2019). "Immunohistochemistry (Ki67) and TUNEL assay results also confirmed that MEG3 expression was negatively correlated with the proliferative activity of tumor cells and positively correlated with the apoptosis of tumor cells." (PMID 31320837, 2019). "Real time PCR showed that the expression of MEG3 was downregulated in the tumor tissues as compared to the adjacent normal tissues." (PMID 31729423, 2019). "The expression of hsa-miR-324-5p, which predictively targeted MEG3, was upregulated in the tumor tissues as compared with the adjacent normal tissues." (PMID 31729423, 2019). "Compared with adjacent non-tumor lung tissues, MEG3 is significantly downregulated in NSCLC tissues." (PMID 31480503, 2019). "The lncRNA maternally expressed 3 (MEG3) has been shown to be an important factor in tumour development." (PMID 31888661, 2019).
tumor (continued). "MEG3 as a kind of tumor suppressor lncRNA, its mechanism of action has been widely studied in the occurrence and metastasis of tumor." (PMID 31488093, 2019). "Experimental studies have demonstrated that MEG3 restoration induced G1 arrest and suppressed xenograft tumor growth in vivo in nude mice." (PMID 31487906, 2019). "Prior studies have supplied compelling evidence that some ncRNAs such as LET, Dreh, MEG3, and H19, are important players in tumor suppression." (PMID 31523930, 2019). "Meg3 is additionally known to act as a tumor suppressor in several types of cancer including leukemia." (PMID 30765776, 2019). "LncRNA MEG3 is considered as a tumor suppressive gene and downregulated in NSCLC cells with DDP resistance." (PMID 31920650, 2019). "To investigate the effect of MEG3 on tumor growth, we transfected MGC-803 cells with MEG3 to observe tumor size and volume." (PMID 31584879, 2019). "The tumor tissues were collected for RT-qPCR and MEG3 expression was confirmed to be high in MEG3 group and low in MEG3 shRNA group (P < 0.05)." (PMID 31320837, 2019). "Among the eight down-regulated genes, one is an oncogene (NEAT1), six are tumor-suppressor genes (ASS1, PTPRD, ISG15, TGFBI, SELENBP1, MEG3) and one gene serves as both an oncogene and tumor-suppressor gene (CDH17)." (PMID 30563222, 2018). "MEG3, located on chromosome 14q32.3 in human genome, was firstly identified as a lncRNA with function of tumor suppressor." (PMID 30579356, 2018). "LncRNA-maternally expressed gene 3 (MEG3) functions as a tumor suppressor in cancers and has been shown to play a vital role in EMT process." (PMID 30282972, 2018). "In the present study, we demonstrated that another lncRNA, Maternally Expressed Gene 3 (MEG3), functioned as a tumor suppressor in GBC." (PMID 30282996, 2018). "Overexpression of MEG3 significantly inhibited tumor growth, and tumor weight was higher in the LV-NC group than the LV-MEG3 group." (PMID 30282996, 2018). "Patients with low MEG3 expression have statistically shorter OS than those with high MEG3 expression, suggesting MEG3 can function as a tumor suppressor and independent predictive factor for TSCC patients." (PMID 29416703, 2018). "MEG3 acts as a tumor suppressor via multiple mechanisms and its expression is decreased across several cancer types, possibly by promoter or Ig-DMR hypermethylation." (PMID 30190790, 2018). "The tumor suppressor role of maternally expressed gene 3 (MEG3) and long non-coding RNA-low expression in tumor (lncRNA-LET) is evident in several gastrointestinal cancers." (PMID 29736267, 2018). "MEG3 is expressed in many normal tissues and has been demonstrated to act as a tumor suppressor in various cancers." (PMID 30282972, 2018). "MEG3 expression negatively correlates with tumor size and TNM stage, thus acting as a potential prognostic biomarker." (PMID 29495592, 2018). "As a maternally expressed imprinted gene representing an lncRNA, MEG3 is widely recognized as a tumor suppressor that is expressed at low levels in some cancers and correlates with prognosis." (PMID 29973283, 2018).